IL2 (interleukin 2)
Diseases named in the same sentence as IL2 in open-access papers (continued):
Sharing a sentence is not in itself a finding about the gene and the disease.
infection (continued). "In general, we have developed and validated a prognostic model to predict the severity of Omicron variant infection based on six predictors: older age, higher numbers of neutrophils, lower numbers of lymphocytes, and higher levels of PCT, IL-2, and IL-10." (PMID 36936976, 2023). "Next, we assessed polyfunctionality of vaccine-induced SARS-CoV-2-specific CD4+ T cells, as multifunctional Th1 cells (IFN-γ+TNF-α+IL-2+) have been described to provide a better correlate of immune protection against infection after vaccination." (PMID 37199415, 2023). "Ancestral infection showed an eightfold increase in IL-2 expression at 2 dpi to 24-fold at 7 dpi, whereas Alpha infection resulted in a higher level of expression with ninefold increase at 2 dpi to 61-fold increase in expression at 7 dpi." (PMID 37507719, 2023). "Corroborating our in vitro observations, a lower proportion of Malat1scr/scr P14 cells produced IL-2 when stimulated ex vivo on day 7 in both infection models." (PMID 38127070, 2023). "Again, spinoculation-based infection of PHA/IL-2-activated T cells with HIV-89.6-EGFP produced EGFP expression in a drug-dependent manner with RetroNectin." (PMID 37563144, 2023). "When comparing the MS (time point t2) and HC cohort after infection, we noted a significantly lower number of IL-2-secreting T cells in MS patients (P = 0.0130)." (PMID 37841269, 2023). "The researchers discovered that leucine supplementation increased the synthesis of interferon-gamma (IFN-), interleukin-2 (IL-2), and tumor necrosis factor-alpha (TNF-), all of which are cytokines linked with improved immune function and infection protection." (PMID 38046946, 2023). "PRRSV-2-specific CD8β+ T cells were mainly IFN-γ or IL-2 or double IFN-γ/IL-2 producers after the single infection." (PMID 37287962, 2023). "Th1 cell population resists intracellular pathogen infection mainly through secreting cytokines IL-2, TNF-B and IFN-γ, thereby mediating the inflammatory response." (PMID 38223593, 2023). "Despite the overall reduction in IL-2 levels due to GA/18β treatments, it was observed that dose B induced IL-2, compared to dose A, in the initial 3 days of infection, a period when disease symptoms are most pronounced." (PMID 38283346, 2023). "The highest frequency of each population was observed at 1 month post-infection, (Median: 0.0093%; 0.012%; and 0.018% for IL2 + / IFNγ-; IFNγ + /IL2-; and IL2 + /IFNγ + CD4 + T cells, respectively)." (PMID 37974069, 2023). "The effect of these drugs on cytokines expression, particularly IL‐2, is crucial to investigate because subclinical infection and clinical illness are common in endemic areas." (PMID 38053473, 2023). "It remains to be investigated if this effect is directly related to the expression of IL-2, or if the LOAd732 infection in DCs leads to less overactivated DCs that are more resistant to suppressive conditions and maintain their T-cell stimulatory function." (PMID 37501121, 2023). "In the context of T cell activation, interleukine-2 (IL-2) is an important cytokine for the recruitment of immune cells and maintenance of the immune response at the infection site." (PMID 38069265, 2023). "The present study aimed to assess the Li specific production of IL‐2 in dogs in different states of infection and correlate these findings with humoral immune response." (PMID 38053473, 2023). "Higher proportions of memory cells were able to produce IL-2 ex vivo at day 31 after infection with either LCMV or LM-GP33 infection, and Malat1scr/scr P14 cells produced equivalent amounts of IL-2." (PMID 38127070, 2023). "IL-2 is mainly produced by the activation of T lymphocytes and plays an important role in immune response and anti-infection." (PMID 36691058, 2023). "Consistent with our previous observations, the IL2-AIS* score showed a progressive decrease during the first 2 months after infection, followed by a gradual recovery towards the baseline level measured in healthy control participants." (PMID 37700317, 2023).
infection (continued). "To that end, we incubated CD4+ T cells with Sotrastaurin (AEB071; 40 μM), a cell-permeant inhibitor of PKC63, during their 48-h activation with PHA and IL-2 and the subsequent 6-h infection with HIV-89.6-EGFP." (PMID 37563144, 2023). "Under stress or infection, the immune activation of sows leads to the activation of pro-inflammatory cytokines including IL-2." (PMID 37689725, 2023). "We concluded that, in order to survive and become memory cells, CD4 effectors generated by infection must again receive signals from cognate recognition and costimulation, resulting in autocrine IL-2, to which they respond and become memory." (PMID 38152398, 2023). "In mouse models, we have provided: in vivo peptide antigen on TLR-activated APC, IL-2:anti-IL-2 Ab complexes, infection surrogates, and others that have supplied PR signals in humans and all enhance CD4 memory and protection." (PMID 38152398, 2023). "The vaccine without PHAD (J8-Lipo-DT), whilst protective cannot rely on cellular immune mechanisms involving IL-17A or IL-2, which significantly protect the host from infection." (PMID 37749129, 2023). "IL-2 is a cytokine that plays a core part in infection by delivering immune signals through IL-2/IL-2R complex." (PMID 36855106, 2023). "Infection with Pb ANKA decreased the concentration of IL-2 in all groups, particularly in the group treated with letrozole + testosterone." (PMID 37384220, 2023). "Conversely, infection significantly reduced levels of IL-1α, IL-2, IL-9, IL-10, IL-12 (p70), IL-13, IFNγ, IL-3, CCL4 (MIP-1β), CSF 2 (GM-CSF), CCL5 (RANTES), and TNFα." (PMID 37790429, 2023). "The opposite trend was true for IL-2 and IL-4 with detected increased expression as infection progressed from 2 to 7 dpi." (PMID 37507719, 2023). "Cultures were performed in the presence of saquinavir, to prevent spreading infection, and low concentrations of IL-2 (10 IU/ml)." (PMID 36420277, 2022). "C. sinensis infection caused diminished Th1 cytokines (IL-1β, IL-2, IL-12p70, IFN-γ and TNF-α), Th2 cytokine (IL-4), as well as Th17 cytokine (IL-17A) in sera, which showed decreasing trend by infection intensity." (PMID 36083861, 2022). "Moderate/severe infection followed by vaccination selectively induced polyfunctional IL-2+/IFN-γ+ SARS-CoV-2 S-specific memory T cells that proliferated extensively in vitro following restimulation." (PMID 36271095, 2022). "Th1 cells secrete IFN-γ, TNF-β, IL-2, etc. to mediate cellular immunity, which effectively defends against infection by intracellular pathogens." (PMID 36439120, 2022). "Cohorts of animals were then treated with either control IgG2a/IL-2 or with anti-IL-2/IL-2 conjugates on days 1, 2, and 3 of infection." (PMID 35944008, 2022). "A previous study revealed that CD4+ MAIT cells also produce more IL-2 cytokine in comparison to other cytokine subsets, indicating their potential role in early infection and latency." (PMID 35056035, 2022). "Th1 cells can then travel to sites of infection where they produce pro-inflammatory cytokines such as IL-2, IFN-γ, and TNF-α, which contribute to the activation of CD8+ T cells and macrophages." (PMID 36255051, 2022). "Comparing cytokine levels between patients with primary and secondary DENV infections, we observed that IL-2, IL-6, IL-31, and IL-12p70 were significantly higher in primary infection and MIP1β was significantly higher in secondary infection." (PMID 35631079, 2022). "During primary infection, neutrophils were able to boost IL-2 and IFN-γ production by CD4+ and CD8+ T cells and IL-17A production by CD4+ T cells." (PMID 35185880, 2022). "Next, in an independent experiment, we analyzed the supernatants from the same cell lines infected with 100 VP/cell collected at day 1, 2 and 3 after infection, for virally produced human IL-2 and TNFα." (PMID 35355980, 2022).
infection (continued). "Serum collected from the post-waned timepoint from these 13 participants (10 post-vaccination and 3 post-infection) underwent in vitro differentiation, wherein the PBMCs were stimulated by recombinant IL-2 and R848 to induce a cellular memory recall response." (PMID 35313572, 2022). "NK cell activation following vaccination and infection can be modulated by antigen-specific CD4+ T cell IL-2 secretion." (PMID 35192547, 2022). "We observed that the overall rate of infection was increased in cells stimulated with IL-15 compared to cells stimulated with IL-2." (PMID 35499323, 2022). "Meanwhile, the high IFN-γ and IL-2 levels in the vaccinated rabbits further inhibited the intracellular infection of E. stiedae." (PMID 36316714, 2022). "Tissue damage and infection induce the activation and release of proinflammatory cytokines, such as IL-1β, IL-2, IL-8, and TNF-α, which mediate the onset of innate immune response." (PMID 36860473, 2022). "Recent clinical studies have reported that low doses of IL-2 can decrease the levels of hormones and reduce the incidence of infection." (PMID 36244973, 2022). "SARS-CoV-2 D614G- and Delta- variant infection induced production of inflammatory cytokines, including high-level of IL-2, GM-CSF, KC at day 3 pi and IL-1β, TNF-α, IL-2, IL-4, IL-6, KC (Neutrophil chemoattractant) at day 7 pi." (PMID 35734088, 2022). "To analyze latency establishment more quantitatively, we determined the outcome of infection in each subset in IL-2 or IL-15 conditions." (PMID 35499323, 2022). "We next compared the overall infection and latency establishment under IL-2 or IL-15 stimulation for all the CD4+ T cells subsets." (PMID 35499323, 2022). "A representative example was the moderated inverse correlation of S‐specific EM CD4+ T‐cell producing IL‐2 in acute infection compared to the direct correlation found 7 months after infection." (PMID 35415890, 2022). "Specifically, we isolated CD4+ T cells from HIV-1 uninfected, deidentified donor PBMCs and activated them with phytohemagglutinin (PHA) and IL-2 for 3 days before infection via spinoculation with HIV ADA." (PMID 36125890, 2022). "The down-regulated IL-2 causes a deficiency in the body’s response to cytotoxins, and the weakened response to cytotoxins makes patients with SLE more vulnerable to infection." (PMID 36536372, 2022). "Serum cytokine levels revealed long-term maintenance of altered profiles even in the case of treatment, with infection increasing IL-2, IL-13, GM-CSF, IL-5, among other cytokines, but these were not markedly altered following treatment (Supplement 1B)." (PMID 35833137, 2022). "A mixed Th1/Th2 immune response (overexpressed IFN-γ, IL-12, IL-2, IL-4, and IL-5) was activated as the infection progressed from 7 to 28 dpi." (PMID 36187827, 2022). "The polyfunctional CD4 T cells producing multiple proinflammatory cytokines (IFN-γ, TNF-α, and IL-2) which one correlate with protection from infection and disease." (PMID 35638072, 2022). "Meanwhile, the high IFN-γ, IL-2, and IL-17 levels in the immunized rabbits further inhibited the intracellular infection of E. magna." (PMID 36713437, 2022). "The optimized approach was associated with more robust Th1 (IFN-γ, TNF-α, IL-2) and Th17 responses (IL-17A) systemically (spleens and PBMCs), but also in the lungs and draining LNs (IFN-γ and IL-17A), the primary site of infection." (PMID 36189260, 2022). "During infection with Heligmosomoides polygyrus, B cell production of IL-2 is required for parasite control." (PMID 35699942, 2022). "PBMCs collected from the post-waned timepoint from these 13 participants (10 post-vaccination and 3 post-infection) underwent in vitro differentiation, wherein they were stimulated by recombinant IL-2 and R848 to induce a memory B cell recall response." (PMID 35632452, 2022). "The literature also pointed out that IL-2 and IL-3 appeared more obvious on the 4th day after infection, and they continued that way up to 14 days." (PMID 35878385, 2022).
infection (continued). "As for the IL-2 condition, the distribution of productive infection was similar to the total infection (middle)." (PMID 35499323, 2022). "We have previously shown in this work that the higher levels of pTEFb expression upon IL-15 stimulation correlated with higher levels of productive infection than IL-2." (PMID 35499323, 2022). "Infections with both T151A and R304M significantly increased the levels of IL-2, IL-17, TNF-β, and CD8 in brain and thymus, IFN-γ in thymus, and CD4 in brain, as compared to infection with the rPS parental backbone virus (P<0.05)." (PMID 36016955, 2022). "We did not detect any significant change in Th1 cytokines (IFN-γ, IL-12, and IL-2) gene expression during early infection." (PMID 36187827, 2022). "In line with previous reports, we observed that when CD4+ T cells are stimulated with IL-15, the global levels of infection increase compared to IL-2 treatment." (PMID 35499323, 2022). "Relatively little is known about coccidian immunity in domestic sheep, although there is convincing evidence that natural infection drives expression of IFN-γ and other Th-1 associated cytokines such as IL-2 and TNF-α36." (PMID 35210503, 2022). "In chickens infected with E. acervulina, increased expression levels of IL-2 were observed after primary and secondary infections." (PMID 35214673, 2022). "The adaptive cytokines IFNγ and IL-2 as well as the IFNγ-induced chemokine IP-10 were the key correlates of prior exposure by infection and vaccination." (PMID 35812430, 2022). "Cytokine gene expression in Caco-2 and RAW 294.7 cells in response to ST infection was quantified, with IL-2, IL-6, and TNF-α having been investigated." (PMID 35438052, 2022). "Neutralization of IL-2 during primary infection promotes antibody responses and can improve protection and reduce disease on reinfection." (PMID 34665220, 2021). "In our analysis, after infection diagnosis in susceptible dogs, PGE2 correlated with TNFα, IL-2, IL-15, and IL-7, most of them with pro-inflammatory functions, possibly attempting to decrease the inflammatory immune response." (PMID 33617528, 2021). "In the CSF, levels of MCP-1, IL-1Ra, IL-2, G-CSF, and IL-18 started increasing on day 5 post-infection." (PMID 34001896, 2021). "As expected, TN were refractory to direct cis infection of HIV-1BaL using either PHA/IL-2- or CCL-19-conditioned medium, while total CD4+ T cells were susceptible to productive cis infection." (PMID 33688006, 2021). "In contrast, T cells differentiated with IL-2-IL-6-IL-23p19-IL-1β expressed both T-bet and RoRγt and significantly inhibited Mtb growth compared to the infection control." (PMID 34299161, 2021). "Thiacloprid led to elevated expression of IL-2, IL-4, IL-10 and downregulated the expression of IgE in mice with secondary infection of AE, and ABZ exerted a consistent effect." (PMID 34488852, 2021). "IL-2 has long been recognized as central to normal immunologic function, including protection against infection." (PMID 33803665, 2021). "Immediately after inoculation, IL-2 levels are lower than our CF controls, and 2 weeks post infection, continue to drop significantly below infection-naïve CF mice." (PMID 34475490, 2021). "To verify the effects of the P80 natural essence also in directly isolated PBMCs, we pre-incubated IL-2-stimulated PBMCs with 1% P80 prior to infection with HIV or HIV-C." (PMID 34579213, 2021). "Surprisingly, levels of IL-2-producing T-cells at three months after vaccination were significantly higher than those produced at three, six, and twelve months after infection (mean SI 15.9 ± 2.3, 8.8 ± 1.6, 10.9 ± 3.0, 9.1 ± 2.1, respectively)." (PMID 34960185, 2021). "This suggests that Th1 cytokines (such as interferon-γ and interleukin-2) induced by infection contributed to the shift from the IgG2 to IgG1 subclasses." (PMID 34395931, 2021).
infection (continued). "This is associated with neonatal Foxp3− CD4+ T cells possessing a significantly increased capacity to produce IL-2 both before and after infection." (PMID 34665220, 2021). "Levels of cytokine-producing T-cells were remarkably stable between three and twelve months after infection, and were comparable to IFNγ+ and IFNγ+IL-2+ T-cell responses but lower than IL-2+ T-cell responses at three months after vaccination." (PMID 34960185, 2021). "Based on our data, we have decided to start administering anti-IL-2 blocking antibody on day -1 and extend the treatment for the first week after infection, therefore avoiding the in vivo IL-2 production peak." (PMID 34869064, 2021). "The upregulation of inflammatory cytokines such as IL-2, IL-6, IL-8, and IL-17A correlated with higher severity of infection and more extreme symptoms such as organ injury." (PMID 34960687, 2021). "When primary and secondary infection was compared within same serotypes, significant difference in expression was observed in IL-2, IL-8, IL-12, IFNγ, GM-CSF, and IP-10." (PMID 34447698, 2021). "In plasma from SLA-stimulated whole blood, the production of IP-10 identified 90% of the patients with asymptomatic infection, but as described in immunocompetent subjects, IL-2 production identified 100% of this population." (PMID 34339445, 2021). "Similar results were obtained with IL-2-stimulated PBMCs, and treatment with P80 natural essence also inhibited productive infection in such cultures." (PMID 34579213, 2021). "By contrast, the levels of NF-κB-mediated IL-2, IFNγ, and perforin, which are primarily produced by T lymphocytes and NK cells, increased significantly during infection, suggesting the establishment of a certain response of these immunocompetent cells." (PMID 34785771, 2021). "These hybridomas showed enhanced IL-2 secretion during infection with ΔPE_PGRS mutants over M. tuberculosis." (PMID 34346699, 2021). "Knockdown of the transcription of either MYD88 or IRAK1 abolished the production of infection-induced proinflammatory cytokines and chemokines, such as interleukin 8 (IL-8), IL-1ꞵ, and IL-2." (PMID 34933448, 2021). "On day eight post-infection, tamoxifen increased IL-2, IL-4, TNF-α and IFN-γ compared to the same group on day four." (PMID 34204678, 2021). "In the rN-BmRON2 and rC-BmRON2 groups, IL-2, IL-4, IL-6 and IL-17a levels peaked on the 21st day after infection, but then decreased rapidly." (PMID 33717108, 2021). "To analyze the impact of opioids on HIV susceptibility and early infection, we removed the opioid drugs following infection and cultured the cells only in R10 with low dose IL-2." (PMID 34452338, 2021). "The percentages and total numbers of CD4+CD25+Foxp3+ T cells diminished within three weeks of infection in animals treated with anti-IL-2 mAb." (PMID 34869064, 2021). "Our results confirm that the frequency of CD4+ and CD8+ T cells producing IL-2 drops along with the acute illness, but a peak of IL-2 production on day four after infection preceded the decay." (PMID 34869064, 2021). "TNF-α has been shown to be a component of killing/control during O. tsutsugamushi infections, and during infection with other intracellular pathogens, either alone or synergistically with IFNγ or IL2." (PMID 34287349, 2021). "Patients who succumbed to infection produced decreased IL-2, IL-4, IL-12, RANTES, tumor necrosis factor alpha (TNF-α), GRO-α, and MIP-1α relative to patients who survived infection." (PMID 33472985, 2021). "At the same time, IL-2 reduces the expression of receptors on antigen-presenting cells, decreasing the rate of their infection with HIV-1." (PMID 34835417, 2021). "Inside both T cell subsets, there was an increased number of central and effector splenic memory T cells 21 days after infection in the group treated with anti-IL-2 mAb." (PMID 34869064, 2021).